PTH1R (parathyroid hormone 1 receptor)
Description:
G protein-coupled receptor for parathyroid hormone (PTH) and for parathyroid hormone-related peptide (PTHLH). Ligand binding causes a conformation change that triggers signaling via guanine nucleotide-binding proteins (G proteins) and modulates the activity of downstream effectors, such as adenylate cyclase (cAMP). PTH1R is coupled to G(s) G alpha proteins and mediates activation of adenylate cyclase activity. PTHLH dissociates from PTH1R more rapidly than PTH; as consequence, the cAMP response induced by PTHLH decays faster than the response induced by PTH.
Synonyms: PTHR; PTHR1; EKNS; PFE
Tractability: Small molecule: a structure with a bound ligand is known; it belongs to a druggable protein family. Antibody: UniProt places it where antibodies can reach, with high confidence; its Gene Ontology location is reachable by antibodies, with high confidence; UniProt predicts a signal peptide or a membrane-spanning region; the Human Protein Atlas places it where antibodies can reach. PROTAC: ubiquitination databases record sites on it; a small molecule that binds it is known. Other modalities: an approved drug acts on it.
Target class: Membrane receptor; Parathyroid hormone receptor; Peptide receptor (family B GPCR); Family B G protein-coupled receptor
Gene: Protein-coding gene on chromosome 3 (46,877,721 to 46,903,799, forward strand). Ensembl gene ENSG00000160801.
Subcellular location: Cell membrane
Subcellular location (Human Protein Atlas): Cytosol; Plasma membrane; Nucleoli
Pathways (Reactome):
Signal Transduction: Class B/2 (Secretin family receptors); G alpha (s) signalling events
Gene Ontology:
Molecular function: G protein-coupled receptor activity; parathyroid hormone receptor activity; peptide hormone binding; protein binding; protein homodimerization activity; G protein-coupled peptide receptor activity; transmembrane signaling receptor activity
Biological process: adenylate cyclase-activating G protein-coupled receptor signaling pathway; adenylate cyclase-modulating G protein-coupled receptor signaling pathway; G protein-coupled receptor signaling pathway; G protein-coupled receptor signaling pathway, coupled to cyclic nucleotide second messenger; intracellular calcium ion homeostasis; phospholipase C-activating G protein-coupled receptor signaling pathway; positive regulation of inositol phosphate biosynthetic process; renal absorption; skeletal system development; cell surface receptor signaling pathway
Cellular component: plasma membrane; apical plasma membrane; basolateral plasma membrane; cytoplasm; nucleus; receptor complex; membrane
Genetic constraint (gnomAD): Loss-of-function variants: 34 observed, 67.84 expected, observed/expected ratio (o/e) 0.5, 90% interval 0.38 to 0.67. The upper end of that interval is the gene's LOEUF score, 0.67, which puts it in group 2 of 6, group 1 being the genes least tolerant of losing a copy. Missense variants: 626 observed, 776.86 expected, observed/expected ratio (o/e) 0.81, 90% interval 0.75 to 0.86. Synonymous variants: 329 observed, 315.32 expected, observed/expected ratio (o/e) 1.04, 90% interval 0.95 to 1.14.
Homologues: Orthologues: chimpanzee PTH1R (99% identical), macaque PTH1R (99% identical), pig PTH1R (94% identical), dog PTH1R (93% identical), mouse Pth1r (90% identical), rabbit PTH1R (90% identical), guinea pig PTH1R (90% identical), rat Pth1r (87% identical), tropical clawed frog pth1r (65% identical), zebrafish pth1r (62% identical). Paralogues in human: PTH2R (45% identical), SCTR (31% identical), VIPR1 (30% identical), ADCYAP1R1 (28% identical), VIPR2 (27% identical), GIPR (27% identical), GLP2R (26% identical), GLP1R (26% identical), GHRHR (25% identical), GCGR (25% identical), CALCRL (23% identical), CALCR (23% identical), and 30 more.
Diseases named in the same sentence as PTH1R in open-access papers:
PTH1R is named in the same sentence as 112 diseases in open-access papers, as found by Europe PMC text mining. Sharing a sentence is not in itself a finding about the gene and the disease. The quoted sentences say what the papers report.
osteoporosis (38 papers, 2009 to 2026). A condition of reduced bone mass, with decreased cortical thickness and a decrease in the number and size of the trabeculae of cancellous bone (but normal chemical composition), resulting in increased fracture incidence. "Development of skeletal diseases such as osteoporosis might be linked to the PTH1R signalling pathway and, consequently, it is crucial to understand the dynamics of PTH-PTH1R binding and subsequent signal transduction." (PMID 36996072, 2023). "A patient with the c.342C>A mutation in the PTH1R gene had multiple manifestations of connective tissue damage, such as knee ligament rupture, congenital heart valve defects, osteoporosis, and scoliosis, which, in general, is characteristic of chondrodysplasia." (PMID 35052464, 2022). "Overexpression of Mettl3 prevented estrogen deficiency‐induced osteoporosis, an age‐related skeletal disorder, by facilitating the translation of Pth1r mRNA, which encodes a protein critical for bone formation, although the functional m6A reader of Pth1r mRNA remains uncharacterized." (PMID 37641471, 2023). "CaSR and PTH1R are pivotal for calcium homeostasis, with CaSR alleles associating with BMD and osteoporosis risk, and PTH1R agonists (e.g., teriparatide) serving as therapeutic agents for osteoporosis by enhancing bone formation 32-35." (PMID 40860192, 2025). "One class of osteoporosis drugs with potential for use in oral regeneration comprises the parathyroid hormone 1 receptor (PTH1R) agonists." (PMID 39347482, 2024). "Although the PTH1R agonist, abaloparatide, has been well established as a bone anabolic agent, it is only clinically approved for treating osteoporosis." (PMID 38540225, 2024). "While PTH1R has been extensively studied in areas such as skeletal development, angiogenesis, osteoporosis, and Ca2+ homeostasis, its role in BTBB function or the diagnosis and treatment of GBM has not been investigated." (PMID 39640361, 2024). "Teriparatide, recombinant parathyroid hormone (PTH[1‐34]), and abaloparatide, an analogue of PTH related‐peptide (PTHrP[1‐34]), are both anabolic medications for osteoporosis that target the PTH receptor PTH1R." (PMID 36530190, 2022). "The protein product of Pth1r can be agonized by abaloparatide and teriparatide, both approved for the treatment of osteoporosis." (PMID 35454087, 2022). "In ACC, PTH1R was also downregulated in both the GEO and TCGA datasets and was the target of osteoporosis drugs." (PMID 35203352, 2022). "Pharmacologically, PTH1R is the major drug target for the treatment of bone-related diseases such as osteoporosis and the disorders in calcium metabolism." (PMID 36271004, 2022). "PTH1R also found to be down-regulated in adrenocortical cancer, was targeted by 3 agonists used in osteoporosis or hypoparathyroidism." (PMID 35203352, 2022). "Multiple analogs of parathyroid hormone, all of which bind to the PTH/PTHrP receptor PTH1R, are used for patients with osteoporosis and hypoparathyroidism." (PMID 33977197, 2021). "Human PTH regulates calcium homeostasis as well as bone formation and resorption via activation of the PTH1R – as such it is a possible target in treating the highly prevalent age-related bone disorder osteoporosis." (PMID 30546309, 2018). "This ability to dissociate arrestin- and G protein-dependent PTH1R signaling in bone will likely influence future therapeutic design for osteoporosis treatment." (PMID 30546309, 2018). "The parathyroid hormone type 1 receptor (PTH1R) is a validated osteoporosis drug target." (PMID 33977197, 2021). "Future studies involving the role of Hh signalling and activation of PTH1R in post-menopausal osteoporosis may offer novel therapeutic interventions." (PMID 33927279, 2021). "In this review, we not only underscore the critical function of PTH1R in bone remodeling and bone physiology but also elucidate the therapeutic potentials of PTH and PTHrP in the management of osteoporosis." (PMID 38474370, 2024).
osteoporosis (continued). "Unlike PTH, a β-arrestin biased PTH isoform (bPTH7-34) appears to uncouple the beneficial anabolic effects of the PTH1R activation from its catabolic and calcitropic negative side effects, thus confirming an effective role for β-arrestin in osteoporosis treatment." (PMID 30546309, 2018).
osteosarcoma (29 papers, 2010 to 2025). A usually aggressive malignant bone-forming mesenchymal neoplasm, predominantly affecting adolescents and young adults. "Recent studies have shown distinct immunostaining for PTH1R in many types of cancers, such as breast, colorectal, and prostate cancers; osteosarcomas; and renal and gastric carcinomas." (PMID 36692956, 2023). "In osteosarcoma, in sharp contrast with what we observed in neuroblastoma, PTH1R overexpression has been described to confer increased proliferative, migratory, and invasive capacities." (PMID 31293052, 2019). "Accordingly, knockdown of PTH1R decreases osteosarcoma invasion and growth, and increases tumor differentiation." (PMID 31293052, 2019). "Taking advantage of the previously reported phenotypes induced by stable knockdown of PTH1R in osteosarcoma, U2OS cell line was simultaneously examined in all these experiments." (PMID 31293052, 2019). "Besides, expression of UNC5B, CAM1, PTH1R, and FCGR3A was significantly associated with survival of patients with osteosarcoma." (PMID 37457661, 2023).
breast cancer (15 papers, 2011 to 2025). A primary or metastatic malignant neoplasm involving the breast. "Together, these analyses of microarray data sets reveal reduced PTH1R expression is often associated with breast cancer progression and bone metastasis." (PMID 36692956, 2023). "Decreased expression of Pth1r is associated with progression and metastasis of breast cancer in both mice and humans." (PMID 36692956, 2023). "Loss of PTH1R signaling in osteoblasts increases migration of 4T1 breast cancer cells in vitro." (PMID 36692956, 2023). "PTH, acting through PTH1R, plays a key role in the bone–breast vicious cycle, altering several key genes implicated in bone metastases and rendering the niche less favorable to the homing of breast cancer cells." (PMID 36692956, 2023). "To examine the role of PTH1R in breast cancer and bone metastasis, we knocked down Pth1r expression in 4T1 cells (Pth1rKD-4T1) by shRNA." (PMID 36692956, 2023). "PTH1R was found to correlate with reduced overall survival in breast cancer patients and was detected in 37% of primary tumors, but 81% of the bone metastasis samples, supporting the role of the PTHrP/PTH1R system in breast cancer bone metastasis." (PMID 37046642, 2023). "In the first study, using 8 different genetically engineered murine models of spontaneous breast cancer, Pth1r was significantly lower in the breast tumor tissue compared with normal mammary gland from pregnant mice on mixed background." (PMID 36692956, 2023). "A total of 10 data sets using murine models of breast cancer, human cell lines, or patient samples were analyzed for PTH1R expression." (PMID 36692956, 2023). "Migration of 4T1 breast cancer cells was increased in the presence of primary calvarial osteoblasts from PTH1R control (PTH1Rfl/fl) or Gsα control (Gsαfl/fl) mice, as compared with wells with serum-containing medium only." (PMID 36692956, 2023). "In a second study using the same MDA-MB-231 human breast cancer cell line, PTH1R expression was significantly decreased in cells from bone metastases compared with naive bone." (PMID 36692956, 2023). "In this study, we establish a critical role for PTH1R in the actions of intermittent PTH in reducing bone metastasis in mouse models of breast cancer." (PMID 36692956, 2023). "To study the role of PTH1R signaling in breast cancer bone metastasis, we attempted to generate PTH1ROsxKO mice that survive to adulthood." (PMID 36692956, 2023). "All 3 murine studies analyzed showed significant decreases in Pth1r expression in breast cancer samples compared with normal breast tissue." (PMID 36692956, 2023). "In contrast to the substantial body of evidence linking PTHrP to breast cancer progression and metastasis, much less is known about PTH1R and its role in cancer metastasis." (PMID 36692956, 2023). "Next, we examined the effects of PTH1R knockdown in breast cancer cells on the tumor–bone microenvironment." (PMID 36692956, 2023). "Here, we examined the role of signaling mediated by PTH 1 receptor (PTH1R) in both osteoblasts and breast cancer cells in influencing bone metastases." (PMID 36692956, 2023). "In this study, we examined the role of PTH1R signaling in both breast cancer cells and osteoblasts in influencing breast cancer skeletal metastases in response to intermittent PTH." (PMID 36692956, 2023). "To examine the relationship between PTH1R expression and breast cancer progression, we analyzed publicly available microarray data sets in the National Center for Biotechnology Information (NCBI) database." (PMID 36692956, 2023). "In conclusion, we demonstrate, using transgenic models and shRNA knockdown, that PTH1R signaling is critical in both breast cancer cells and osteoblasts for the inhibitory actions of PTH treatment on bone metastases." (PMID 36692956, 2023). "In order to test this idea, we isolated cells from mammary tumors taken from Tet-PTHrP;PyMT mice and first confirmed that they expressed the PTH1R." (PMID 35440032, 2022).
breast cancer (continued). "PTH1R is expressed in many tissues that also express PTHrP, including breast cancer cells.The anabolic actions of PTH on PTH1R are mediated by the stimulatory G protein Gs, which activates adenylyl cyclase, leading to an increase in cAMP levels and the activation of the PKA pathway." (PMID 36692956, 2023). "In conclusion, PTH1R expression is crucial in both osteoblasts and breast cancer cells for PTH to reduce bone metastases, and in breast cancer cells, this may be mediated in part by suppression of PTHrP." (PMID 36692956, 2023). "Besides, RUNX2 also can activate Indian Hedgehog expression and further increase PTH1R levels in breast cancer metastatic bone disease." (PMID 35534547, 2022). "Consequently, the downregulated LIFR promoted MCF-7 cell exit from dormancy, suggesting that inducing and maintaining LIFR, a downstream factor of PTHrP/PTH1R, might keep tumor cells in a dormant state to prevent overt bone metastasis in breast cancer." (PMID 37046642, 2023). "Collectively, these data suggest an interplay of events among PTH1R, PTH, and PTHrP, particularly in breast cancer–mediated skeletal metastasis, and offer new directions for research." (PMID 36692956, 2023). "Ablation of Gsα, a downstream mediator of PTH1R signaling in bone, abolishes the inhibitory effects of PTH treatment on breast cancer bone metastasis." (PMID 36692956, 2023). "Using shRNA and transgenic models with impaired PTH1R signaling, we demonstrate that PTH1R is required in both breast cancer cells and osteoblasts for PTH to reduce breast cancer bone metastases in mice." (PMID 36692956, 2023). "Bone disseminated breast cancer cells secrete osteolytic factors like PTHrP, which induces receptor activator of nuclear factor-κB ligand (RANKL)-dependent osteoclastogenesis through PTH1R activation on osteoblasts." (PMID 38409028, 2024). "Intermittent PTH also did not reduce bone metastasis when expression of PTH1R was knocked down in 4T1 murine breast cancer cells by shRNA." (PMID 36692956, 2023). "Migration of 4T1 breast cancer cells was further increased toward primary calvarial osteoblasts lacking either PTH1R or Gsα, suggesting that PTH1R signaling in osteoblasts negatively regulates secreted promigratory factors acting on breast cancer cells." (PMID 36692956, 2023). "Additionally, differences in phenotypes between the PTHrP mutant cells are likely not due to paracrine effects of secreted PTHrP since we and others have previously shown that PTHrP does not activate PTH1R or downstream cAMP signaling in breast cancer cells." (PMID 38409028, 2024). "Interestingly, evidence exists suggesting that multiple breast cancer cell lines express PTH1R at varying levels, but do not activate downstream cAMP signaling in response to PTH or PTHrP, despite functional signaling in response to calcitonin and PGE2 which serve as positive controls." (PMID 33828987, 2021). "However, the functional relevance of this pattern of receptor expression in bone-disseminated tumor cells is still unclear since in vitro data indicate that in ER+ breast cancer cells, activation of PTH1R/cAMP signaling does not regulate dormancy gene expression." (PMID 33828987, 2021). "Significantly higher values of RANKL, CTKS, PTH1R, IL-6, IL-1β and MMP-1 were found in bone fragments cultured with MCF-7 breast cancer cells in comparison to bone fragments cultured without cancer cells, both in normoxic and hypoxic conditions." (PMID 27765913, 2016).